Y_RNA (Y RNA )
Gene: Miscellaneous RNA gene on chromosome 11 (118,994,560 to 118,994,655, forward strand). Ensembl gene ENSG00000283691.
Homologues: Orthologues: chimpanzee Y_RNA (100% identical). Paralogues in human: RNY4 (92% identical), RNY4P14 (92% identical), RNY4P7 (91% identical), RNY4P10 (90% identical), RNY4P3 (90% identical), RNY4P6 (90% identical), Y_RNA (90% identical), Y_RNA (89% identical), RNY4P17 (88% identical), RNY4P24 (88% identical), RNY4P25 (88% identical), Y_RNA (88% identical), and 88 more.